BDNF (brain derived neurotrophic factor)
Diseases named in the same sentence as BDNF in open-access papers (continued):
Sharing a sentence is not in itself a finding about the gene and the disease.
depression (continued). "Therefore, BDNF is a vital link in the pathogenesis of depression." (PMID 37626579, 2023). "In particular, in the near future, BDNF levels could be used to support the diagnosis of BD, to improve precision in the detection of early stages of BD, and to differentiate between BD and other affective disorders, such as major depressive disorders." (PMID 37626577, 2023). "In addition, BDNF may be an effective target for the treatment of comorbid diabetic NP and depression." (PMID 38179224, 2023). "Hence, based on the neuroinflammatory hypothesis of depression, we investigated the concentration of two opposite-acting adipokines (anti-inflammatory adiponectin and proinflammatory resistin) and BDNF in antidepressant-resistant patients undergoing ECT." (PMID 37891727, 2023). "The BDNF-TrkB signaling pathway has been previously demonstrated to modulate brain inflammation and protect against hippocampus injury, suggesting that ADSC-mediated protective effects could be linked to reduced symptoms of depression." (PMID 36986674, 2023). "Previous studies have confirmed BDNF-TrkB and related pathways downstream of its biological function, most of which adopt methods such as inducing excitatory neurotoxicity by glutamate, creating epileptic convulsions or depression models, or increasing exogenous BDNF." (PMID 37884604, 2023). "The neurotrophic factor hypothesis focuses on the brain-derived neurotrophic factor (BDNF) and suggests that an imbalance of brain derived neurotrophic factor precursor (proBDNF) and mature form of brain-derived neurotrophic factor (mBDNF) is closely related to the development of depression." (PMID 36985457, 2023). "Importantly, reduced BDNF, and increased total glucocorticoid receptor (GR) and phosphorylated GR (at serine 211) in depression animals were also reversed by PRE, suggesting an antidepressant effect of P. resupinata through the BDNF-and/or GR-mediated molecular mechanism." (PMID 37781095, 2023). "Nonetheless, according to the neurotrophic hypothesis, depression could be the result of the stress-induced reduced expression of neurotrophic factors such as Brain-Derived Neurotrophic Factor (BDNF), IGF-1 or Glial cell line-derived neurotrophic factor (GDNF)." (PMID 37894932, 2023). "Hence, lower serum zinc concentrations could compromise serotonin and BDNF activity and diminish neurogenesis, which may be the pathophysiology of depression." (PMID 37434135, 2023). "Hence, exogenously supplying BDNF is a promising strategy for treating depressive disorder." (PMID 37848975, 2023). "In addition, a study using low-dose ozone to treat insomnia in patients with coronary heart disease found that low-dose ozone therapy improved sleep quality and ameliorated depression by elevating the levels of brain-derived neurotrophic factor (BDNF) in blood serum." (PMID 37214227, 2022). "Besides the newly raised immune-inflammation theory, the hyperactivity of the hypothalamic-pituitary-adrenocortical (HPA)-axis, the brain-derived neurotrophic factor (BDNF) deficiency, and the dopamine (DA) deficiency have been demonstrated in the occurrence and development of depression." (PMID 35295780, 2022). "Notably, BDNF in the HC produces effects that are opposite to those induced in the mesolimbic pathway in behavioral models of depression; therefore, caution should be exerted in developing therapies for depression having a single effect on BDNF all over the brain." (PMID 36499323, 2022). "Interestingly, BDNF constitutively controls the nuclear translocation of the master redox-sensitive transcription factor Nrf2, which activates antioxidant defenses, highlighting the inter-relationships between BDNF, oxidative stress, and depression." (PMID 35406124, 2022). "Therefore, BDNF protects against stress-induced neural damage, and it affects neurogenesis in hippocampal neurons, which is thought to be involved in the induction of depression." (PMID 36499295, 2022).
depression (continued). "Further, an increased instance of BDNF gene methylation was reported in heterozygous (Val/Met) older women with anxiety/depression compared to those who were homozygous (Val/Val), again implying that there may be sex-specific consequences of Met allele expression." (PMID 35887357, 2022). "In addition, exercise among patients with depression upregulated brain-derived neurotrophic factor (BDNF), which stimulates and mediates neurogenesis and regulates depressive behavior, in the hippocampus and cortex, promoted hippocampal neurogenesis, and significantly enhanced synaptic plasticity." (PMID 35227300, 2022). "Inhibition of miRNAs may activate the BDNF-TrkB pathway for treating depression in the hippocampus." (PMID 35543383, 2022). "Stress and depression could prompt impairments of cellular resilience by reducing the BDNF levels." (PMID 36501051, 2022). "In summary, preclinical and clinical evidence shows that 5-HT and BDNF have a bidirectional relationship, where the modification of one may affect the other, which can have a direct impact in the establishment of both depression symptoms and the therapeutic effects of antidepressants." (PMID 36142808, 2022). "Therefore, our current research further revealed that XYP can improve hippocampal neuron injury in CUMS-induced depression model rats, and its mechanism might be in connection with GR and BDNF." (PMID 34984950, 2022). "Further dissection of the role of BDNF and TrkB signaling in the hypothalamus and connected regions and how it may be affected by stress and sex will greatly enhance our understanding of cardiovascular responses in depression pathology." (PMID 36466807, 2022). "In addition, BDNF insufficiency also causes cognitive alterations in mice and humans, such as elevated aggression, anxiety and depression-like behaviors, and a lack of learning modulation." (PMID 35628626, 2022). "Moreover, cognitive impairment and depression in HF may be related to brain-derived neurotrophic factor (BDNF)." (PMID 36490252, 2022). "Moreover, alarin may help alleviate depression by increasing the expression of brain-derived neurotrophic factor (BDNF) in the prefrontal cortex and hippocampus, which has antidepressant-like actions through neuroprotection and promoting synaptic plasticity." (PMID 36246892, 2022). "It was also hypothesized that CBD increased BDNF to alleviate depression." (PMID 36430254, 2022). "Moreover, the stimulatory effect of vitamin D3 on brain-derived neurotrophic factor (BDNF) signaling and neuroplasticity may play a role not only in the recovery of neurological functions, but also in ameliorating post-stroke depression and anxiety." (PMID 36358492, 2022). "Finally, the molecular mechanisms underlying the relation between BDNF and the emerged miRNAs affecting obesity, depression and CVD have not been investigated as yet." (PMID 35911513, 2022). "As a result, the downregulation of BDNF may induce depression." (PMID 36499295, 2022). "In short, Geum japonicum, garlic essential oil, fish oil, conjugated linoleic acid, and anthocyanin could ameliorate depression through increasing the production of BDNF, nerve growth factor, and neurotrophin-3, and their effects and mechanisms should be further investigated by clinical trials." (PMID 36358502, 2022). "In rodents, the balance between mature BDNF and proBDNF has been proven to play an important role in depression-like behaviors induced by chronic unpredicted mild stress, and a decrease in the ratio of mBDNF/proBDNF could induce a reduction in the dendritic spine density of hippocampal neurons." (PMID 35624812, 2022). "Furthermore, antidepressants could improve the expression of BDNF in brain, which further alleviates depression symptoms." (PMID 36158555, 2022). "Indeed, BDNF deregulation has been associated with neurodevelopmental, neurological, and neurodegenerative disorders including RTT, Alzheimer’s disease, Parkinson’s disease, depression, and drug addiction." (PMID 35563748, 2022).
depression (continued). "Therefore, based on the results obtained in this study, we hypothesized that S-ketamine mediated synaptic structure through SIRT1 and BDNF in depression." (PMID 35664490, 2022). "Moreover, patients experiencing post-stoke depression present with lower serum BDNF levels." (PMID 35743624, 2022). "However, increased levels of BDNF have a protective effect against depression." (PMID 35886019, 2022). "Therefore, in addition to other mechanisms, a decrease in BDNF levels may be a possible reason for the inflammation-induced development of depression." (PMID 36578534, 2022). "Brain‐derived neurotropic factor (BDNF) may also play an important role in depression." (PMID 35875370, 2022). "However, Bifidobacterium longum EPS significantly suppressed LPS-induced anxiety-/depression-like behaviors, hippocampal NF-κB+/Iba1+ cell population, and blood LPS level and induced LPS-suppressed hippocampal BDNF+/NeuN+ cell population and claudin-5 expression." (PMID 35672451, 2022). "Lower thickness and volume could be a consequence of depression episodes and be related to other disturbances also seen in depression, such as inflammation, lower brain-derived neurotrophic factor (BDNF) levels, or increased activity of HPA-axis related processes." (PMID 36088843, 2022). "The molecular mechanisms underlying these oxidative stress-related anxiety-like behaviors may be related to a decrease in brain-derived neurotrophic factor (BDNF) levels and, interestingly, the depression-like phenotype may be reversed by treatment with antioxidants." (PMID 35406124, 2022). "Thus, we hypothesized that inflammation-activated C/EBPβ could mediate HFD-induced depression by downregulating BDNF and promoting AMPARs internalization." (PMID 36578534, 2022). "Therefore, a significant positive correlation can exist between BDNF levels and depression." (PMID 36499295, 2022). "Furthermore, increasing the levels of 5-HT and BDNF could alleviate depression, the mechanism of which might be related to the gut microbes." (PMID 36422003, 2022). "Therefore, deletion of BDNF has a strong enhancing effect on depression." (PMID 34984950, 2022). "For instance, on the one hand, although the serum BDNF level in active rTMS group only showed a marginally significant increase compared with sham rTMS group, no noticeable associations were detected between baseline BDNF level, severity of depression and cognitive functions." (PMID 35912517, 2022). "In addition, studies have also found that: after rTMS treatment, the levels of brain-derived neurotrophic factor in peripheral blood of patients with depression was higher than before, which may be one of the mechanisms of rTMS." (PMID 35711903, 2022). "Moreover, we further demonstrated that XYP also could upregulate GR, p-GR, and BDNF in CUMS-induced depression model rats." (PMID 34984950, 2022). "Additionally, L7Gn increased BDNF mRNA and protein levels, which were reduced by SD stress, and an L7Gn intervention resulted in the upregulation of TrkB, ERK, and CREB, which are downstream molecules of BDNF signaling, reducing depression in rat and mouse models of inflammation." (PMID 36499295, 2022). "Furthermore, Bifidobacteria-fermented red ginseng exerted protective effects against Escherichia coli-induced depression by enhancing the abundance of Bacteroidetes, decreasing the abundance of Proteobacteria, and upregulating the expression of BDNF mediated by NF-κB." (PMID 36358502, 2022). "In addition, previous evidence suggests that BDNF may be involved in depression, such that the expression of BDNF is decreased in depressed patients." (PMID 36499295, 2022). "The products of BDNF may promote neurogenesis and protect against excitotoxicity in both the hippocampus and striatum and mediates the increase of amygdala volume in samples of patients with drug-induced depression." (PMID 35431790, 2022).
depression (continued). "In addition, we provided evidence that the amount of circulating BDNF can reflect the EV-derived miRNAs related to CV disease and depression, supporting the hypothesis that BDNF may be the link between mood disorders and cardiometabolic diseases." (PMID 35911513, 2022). "In addition, the serum BDNF level was also found to be decreased in depression patients, and the level of plasma BDNF seems to be lower in patients with severe depression compared to mild depression patients." (PMID 36158555, 2022). "Notably, some studies correlated low circulating levels of BDNF with depression in PD patients." (PMID 35210396, 2022). "Studies have revealed that in immobilization and Escherichia coli (EC) induced anxiety or depression mice, Rd could reduce depression and colitis by regulating NF-kB-mediated BDNF expression and intestinal Flora imbalance, eventually ameliorating depressive behaviors." (PMID 35795547, 2022). "BDNF, a member of the neurotrophin family, plays a critical role in synaptic plasticity and long-term memory; it also participates in the pathophysiology of multiple psychiatric disorders, including depression, post-traumatic stress disorder, schizophrenia, and obsessive–compulsive disorder." (PMID 36578534, 2022). "Increased expression of BDNF in the brain may be an effective treatment for depression." (PMID 36297505, 2022). "Furthermore, the BDNF level of individuals with severe stress, anxiety, or depression is prone to stay at a low level, which might lead to aggravating sleep health problems." (PMID 36231626, 2022). "However, many scientists have proposed that brain‐derived neurotrophic factor (BDNF) might play a significant role in the pathophysiological mechanism of depression." (PMID 35510613, 2022). "In addition to the increase in oxidative stress in the hippocampi of depression model mice, a decrease in the antioxidant activity and BDNF levels have also been reported, which suggests that there is a negative correlation between oxidative stress and BDNF levels." (PMID 36299904, 2022). "Furthermore, it has recently been shown that the administration of L. helveticus R0052 and B. longum R0175 caused an increase in the concentration of Brain Derived Neurotrophic Factor (BDNF) in the blood, which may reduce the severity of depression symptoms." (PMID 36079082, 2022). "The Yin and Yang hypothesis of BDNF has provided significant insight into depression." (PMID 35510613, 2022). "In addition to BDNF, also IGF-1, FGF-2, and NGF have been implicated in depressive disorders." (PMID 35886944, 2022). "Furthermore, in OA participants with MDD, the negative correlation between BDNF levels and the HAMD-17, SDS, and VAS scores suggests that the decrease in serum levels of BDNF may reflect the severity of depression and pain." (PMID 36386998, 2022). "Moreover, antidepressants are known to improve BDNF expression in the brain, which may reduce the symptom of depression." (PMID 34093193, 2021). "Furthermore, psychobiotics have demonstrated efficacy in reducing some physiological outputs of anxiety and depression such as immune function, corticosterone/cortisol, neurotransmitters, and brain-derived neurotrophic factor (BDNF) in animal and human studies." (PMID 34589719, 2021). "It is unclear whether low BDNF levels in patients with depression are primary or secondary." (PMID 34362162, 2021). "Considering that BDNF protein and mRNA levels are decreased in the ventral hippocampus of SERT−/− rats, we sought to investigate whether BDNF gene overexpression in the ventral hippocampus was able to restore BDNF levels and anxiety- and depression-like behavior in SERT−/− rats." (PMID 34068707, 2021). "In addition, interaction of OST with BDNF may also contribute to OST’s ability to rescue the OVX-induced cognition deficit and alleviate depression-like behaviors since BDNF also plays a key role in cognition and in alleviating depression-like behaviors." (PMID 34025413, 2021).
depression (continued). "In addition, neuroimaging studies have revealed a reduced hippocampal volume in some patients with depression, which is speculated to be related to a decrease in the levels of neurotrophins, such as brain-derived neurotrophic factor (BDNF)." (PMID 34421705, 2021). "In addition to BDNF, serotonin plays an important role in MS-induced depression." (PMID 34890365, 2021). "However, acute HIIE increases serum BDNF concentration and attenuates tension, depression, and anger mood states independently of menstrual phase, suggesting the possibility of using HIIE as a strategy to attenuate the deleterious sensations occasioned by ovarian hormonal fluctuations." (PMID 33603039, 2021). "Moreover, some studies indicate the presence of an interplay between NF-kB and brain-derived neurotrophic factor (BDNF), which is a cornerstone of the neurotrophic hypothesis of depression." (PMID 33946816, 2021). "Thus, BDNF may play a vital role in the pathogenesis of depression and should be included within the restorative impacts of antidepressants." (PMID 33506043, 2021). "Previous reports show that low levels of BDNF in the hippocampus may lead to some functional and structural alterations in hippocampal neurons, induce depressive-like behaviors in rodents, and ultimately contribute to the symptoms of depression in humans." (PMID 33833828, 2021). "Because AT is a food-derived product, daily intake of AT may confer resistance to stress-induced or aging-related neurological diseases such as depression and dementia, which is likely mediated by AT-induced BDNF expression in neurons in addition to ET-mediated neurogenesis in neural stem cells." (PMID 34977362, 2021). "The present study investigated whether Xuefu Zhuyu decoction can improve the angina pectoris-specific health status and depressive symptoms of angina pectoris patients by analysing the Hamilton Depression Rating Scale, as well as serum concentrations of BDNF, serotonin, and ATP." (PMID 34567219, 2021). "The aim of this review was to provide information of the biological markers of depression such as monoamines, tryptophan, endocannabinoids, markers of inflammatory processes (oxidative stress and cytokines) stress and sex hormones and their relationship to BDNF." (PMID 34300001, 2021). "Depression might be triggered by HFD through AMPK/CREB/BDNF pathway." (PMID 34054732, 2021). "Our results provide the first evidence that d-serine exerts antidepressant-like effects in mice mediated through restraining BDNF signaling pathway and regulating synaptic plasticity in NAc, implying that d-serine may be an effective therapeutic agent toward depression." (PMID 34654365, 2021). "In an animal study that employed corticosterone to induce depression-like behaviour, chronic exposure to lavender EO prevented such negative effects of depression as suppressed neurogenesis, suppressed dendritic growth of immature neurons and decreased serum BDNF levels." (PMID 34063646, 2021). "Based on these results, the authors hypothesized that childhood trauma may permanently reduce (“blunt”) the responsiveness of the neurotrophic system to SSRI usage and that this responsiveness might be more important for depression course than the actual BDNF serum levels." (PMID 33643008, 2021). "However, the molecular mechanism of BDNF protein expression in depression is still obscure." (PMID 32203159, 2021). "Inflammation-induced depression also occurs after exposure of rodents to the viral mimetic poly I:C, which binds to TLR3 and the Rig-I-like receptor (RLR) MDA5 and has been associated with reduction in brain-derived neurotrophic factor (BDNF) signaling and increased levels of kynurenine." (PMID 33921690, 2021).